HAVCR2 (hepatitis A virus cellular receptor 2)
Diseases named in the same sentence as HAVCR2 in open-access papers (continued):
Sharing a sentence is not in itself a finding about the gene and the disease.
cancer (continued). "Finally, we gathered the IC50 of a wide variety of drugs among different cancer cell lines through the GDSC and CTRP databases and tried to explore the possible associations with the corresponding CXCL13, HAVCR2, LAG3, TIGIT, PDCD1, and LAYN mRNA values." (PMID 39064019, 2024). "Notably, our correlation analysis results showed that OLR1 was positively correlated with most immune checkpoint molecules in the majority of cancer types, with a particularly strong correlation with HAVCR2." (PMID 37629087, 2023). "HAVCR2/TIM-3 is an emerging clinical target in the cancer immune landscape along with VISTA." (PMID 36968142, 2023). "Stem-cell-originating cancer cells co-localized with CD4+ T-cells expressing a high frequency of FOXP3+ cells, as well as upregulation of genes associated with exhaustion including Pdcd1, Ctla4, and Havcr2 (TIM3)." (PMID 37654482, 2023). "The results demonstrated that SERPINE1 expression was positively correlated with the expression of most inhibitory immune checkpoints, including CD274 (PD-L1), PDCD1 (PD-1), CTLA4, and HAVCR2 (TIM-3) in most cancers, especially GBM-LGG, KIPAN, UVM, PAAD, and COAD-READ." (PMID 37680718, 2023). "Interestingly, IL-6 targeting by antibodies was found to induce synergistic T cell killing effects when combined with T cell immunoglobulin and mucin-domain containing-3, also known as HAVCR2 receptor (TIM-3/ HAVCR2) therapy, in animal cancer models." (PMID 36980527, 2023). "Notably, except for DLBC and TGCT, OLR1 exhibited positive correlations with most immune checkpoint molecules in almost all cancers, with a particularly strong correlation with HAVCR2." (PMID 37629087, 2023). "The results of the association between IFN-γ score and ICG indicated that the IFN-γ scores of virtually all of the different cancers that were investigated had a positive association with the expression of TIGIT, IDO1, ICOS, CD86, CTLA4, HAVCR2, PDCD1LG2, and CD48." (PMID 37646041, 2023). "Therefore, FCGR3A and HAVCR2 are highly expressed in various cancer models and are likely to participate in the immune process of NK cells." (PMID 36505767, 2022). "Epigenetic changes of HAVCR2 were observed in many types of cancer." (PMID 36081997, 2022). "The CAFDL signature was significantly positively associated with TGFB1, CD276, CD40, VEGFA, VEGFB, etc., but showed significantly negative correlation with immune checkpoints (such as CD274, PDCD1, CTLA4, TIGHT, and HAVCR2) and anti-cancer immune regulators (IFNG, IDO1, and GZMA)." (PMID 35967425, 2022). "Our results illuminated that DNA methylation of HAVCR2 was dysregulated in different cancers." (PMID 36081997, 2022). "All these findings together suggested that ADH1B, LAG3, and HAVCR2 were significantly down-regulated in cancer tissues, which would offer a good prospect that targeted ADH1B could increase the therapeutic efficacy of OV patients." (PMID 35756990, 2022). "The observed results suggested that HAVCR2 gene expression had multiple effects on cancer immunity." (PMID 36081997, 2022). "Moreover, HAVCR2 was the most correlated gene with the infiltration of B and T cells, suggesting that HAVCR2 is a potential target for cancer immunotherapy." (PMID 35198632, 2022). "We further explored the alterations of HAVCR2 in pan-cancer using the cBioPortal database." (PMID 36081997, 2022). "Notably, CD274/PD-L1, PDCD1LG2/PD-L2, PDCD1/PD1, cytotoxic T lymphocyte-associated antigen 4 (CTLA4), T cell membrane protein 3 (TIM3; also known as HAVCR2), and lymphocyte activation gene 3 (LAG3) were correlated to FAM72A across different cancers." (PMID 36613817, 2022). "We further explored the correlation between YTHDC2 and eight immune checkpoint‐related genes and found that YTHDC2 was significantly associated with the expression of SIGLEC15, IDO1, CD274, HAVCR2, PDCD1, CTLA4, LAG3 or PDCD1LG2 in almost all types of cancers except for CESC and TGCT." (PMID 34312987, 2021).
cancer (continued). "Immune exhaustion marker genes (such as PD-L1, CTLA-4, LAG-3 and HAVCR2) have been demonstrated to play significant role in immune suppression in multiple tumors and several target inhibitors have also been widely applied to immunotherapy for cancers." (PMID 34844602, 2021). "Particularly, CD48, HAVCR2, LAG3, and TIGIT were identified as novel immunotherapeutic targets of several cancers, suggesting that the low-risk OS patients might benefit from their candidate inhibitors." (PMID 32908905, 2020). "Variants of TIM-3/HAVCR2 3′UTR miRNA binding sites are significantly associated with cancer; however, roles in post-transcriptional regulation have not been elucidated." (PMID 29796301, 2018). "Our findings indicate that the 3′UTR variants regulate the activity of TIM-3/HAVCR2 and could aid in targeting the TIM-3/HAVCR2 pathway for cancer treatment." (PMID 29796301, 2018). "Additionally, TIM-3/HAVCR2 is intimately involved in the pathogenesis of malignant tumors and progression of various types of cancer." (PMID 29796301, 2018). "Ligand LGALS9 with its receptors (CD44, CD47, and HAVCR2) showed that the inflammatory meta program also interacted with immune cells, implying that it is a cysteine/galactose binding protein that can compromise the functions of NK and T cell to facilitate cancer cell immune escape." (PMID 38944814, 2024). "Moreover, the advantages of blocking HAVCR2 have been indicated in preclinical cancer models." (PMID 38568056, 2024). "Moreover, immune checkpoint genes (such as PD1/PD-L1, LAG-3, CTLA-4, and HAVCR2) have been certified to participate in the immune suppression process of multiple tumors and targeted inhibitors have also been applied to specific immunotherapy for cancers." (PMID 35754848, 2022). "This may suggest that TIM3 (HAVCR2) agonists may have a role in these cancer types." (PMID 36224560, 2022). "However, the expression of other T-cell inhibitory receptors, such as Tim-3 (Havcr2) or Lag-3, and the cancer immune evasion-related factor Pak4 remained unchanged in MUP-uPA mice, regardless of the type of diet fed in parallel to the unchanged expression of indoleamine 2,3-dioxygenase (Ido1)." (PMID 34439245, 2021). "The genetic variations of TIM-3/HAVCR2 may contribute to the development of cancers." (PMID 29796301, 2018). "The correlation between SLC2A1 expression and eight immune checkpoints (CTLA4, PDCD1, TIGIT, LAG3, CD274, HAVCR2, PDCD1LG2, and SIGLEC15) was further investigated across multiple cancer types." (PMID 40824962, 2025). "Previous studies have highlighted the differential expression patterns of HAVCR2, TIGIT, LAG3, LAYN, and CXCL13, showing strong correlations with survival outcomes across multiple cancer types." (PMID 40076932, 2025). "The mRNA expression of HAVCR2 strongly activated apoptosis (31%), EMT (41%), hormone ER (34%), RTK (6%), and PI3KAKT (6%) pathways in pan-cancer." (PMID 40076932, 2025). "TMED2 expression was positively connected with important immune checkpoint markers such as CD274, HAVCR2, PDCD1LG2, and SIGLEC15 in numerous cancer types." (PMID 40519935, 2025). "Subsequently, we analysed the expression levels of these genes across 33 types of cancer and found that AXL, MERTK, TYRO3, CD24, HAVCR2 and CD47 exhibited higher expression levels, while TIMD4 and HAVCR1 showed relatively lower expression." (PMID 40576208, 2025). "The mRNA expression profile of six Tex markers, LAG-3, PDCD1, TIGIT, HAVCR2, CXCL13, and LAYN was investigated in pan-cancer." (PMID 40076932, 2025). "We initially explored the expression of the Tex signature genes (LAG3, TIGIT, LAYN, PDCD1, HAVCR2, and CXCL13) in pan-cancer." (PMID 39064019, 2024). "Then, immune checkpoints analysis shown that UBE2C had a negative correlation with immune checkpoints, such as CD274(PD-1), PDCD1(PD-L1), CTLA4, TIGIT, LAG3, HAVCR2, and PDCD1LG2 in a great many cancers." (PMID 38370368, 2024).
cancer (continued). "HAVCR2 has been recently found to contain enrichment of methylation sites inside the 3′ UTR, suggesting that this region is a potent target for cancer therapy and a new biomarker for better diagnosis and prognosis of tumors." (PMID 39064019, 2024). "Subsequently, we also explored the correlation between the expression levels of LRP6 and the expression levels of common immune checkpoints in 33 cancers, such as SIGLEC15, IDO1, CD274, HAVCR2, PDCD1, CTLA4, LAG3 and PDCD1LG2." (PMID 38226972, 2024). "Other immune checkpoints, including LAG‐3, TIM‐3 (also known as HAVCR2), TIGIT, and VISTA, have emerged as promising targets in cancer immunotherapy." (PMID 37904707, 2023). "A number of inhibitory immunoreceptors have been identified and studied in cancer in past decades, including but not limited to PD-1, PD-L1, CTLA-4, LAG3, HAVCR2, TIGIT, CD69 and CD40." (PMID 37989761, 2023). "PILRΑ expression had a close and positive correlation with three ICGs including LAIR1, HAVCR2 and CD86 in almost all cancer types." (PMID 37652967, 2023). "We analyzed the expression profile of COMMD2 gene and ICGs (CD274, CTLA4, HAVCR2, LAG3, PDCD1, PDCD1LG2, SIGLEC15, and TIGIT) at a pan‐cancer level." (PMID 36205192, 2023). "Since immune checkpoint inhibitors (ICIs) have been a prominent topic in cancer treatment, the expression of eight ICIs (LAG3, HAVCR2, CD27, TNFRSF14, CTLA4, TMIGD2, TIGIT, and PDCD1LG2) were analyzed between groups in the study." (PMID 37405988, 2023). "We found that PTPN6 expression was positively correlated with PDCD1, CD274, CTLA4, LAG3, HAVCR2, and CD244 in most cancer types in TCGA, including LGG and GBM." (PMID 37737713, 2023). "Other immune checkpoint ligands or receptors, SELPLG, HAVCR2, LGALS3, and LGALS9, were highly expressed in cancer cells or other infiltrating cells." (PMID 36529697, 2023). "Subsequently, the correlation between key pan-carcinoma molecules (including CTLA4, PDCD1LG2, IDO1, and HAVCR2) and CD86 was calculated." (PMID 37064861, 2023). "The key immune checkpoints (CD274, CTLA-4, HAVCR2, LAG3, PDCD1, PDCD1LG2, SIGLEC15, and TIGIT) also had a significant relationship with DTYMK expression in approximately 20 kinds of cancers, except in MESO, PCPG, and UCS." (PMID 36094557, 2022). "As more and more ICIs have been proven to be effective in cancer treatment in recent years, we further evaluated the expression of PD-1, PD-L1, CTLA4, and HAVCR2." (PMID 36160015, 2022). "In contrast, VSIR, HAVCR2, and CD86 were negatively correlated with METTL3 expression in several cancer types." (PMID 36614956, 2022). "The findings reveal that COMP was positively correlated with a majority of immune inhibitors and stimulators in several cancers, with TNFSF4, an immune stimulator, and HAVCR2, an immune inhibitor, exhibiting the strongest correlation with COMP." (PMID 36551305, 2022). "RALA was significantly correlated with the infiltration of B cells and macrophages, as well as the expression of immune checkpoint molecules such as CD274, CTLA4, HAVCR2 and LAG3, suggesting that RALA can be used as a kind of new pan-cancer immune marker." (PMID 36466919, 2022). "Afterward, we evaluated the link between DTYMK expression and key immune checkpoints (CD274, CTLA-4, HAVCR2, LAG3, PDCD1, PDCD1LG2, SIGLEC15, and TIGIT) expression levels in pan-cancer." (PMID 36094557, 2022). "Malignant tumors can evade immune killing by stimulating immune checkpoint target genes (such as PD-1, PD-L1, CTLA-4, TGF-β, and HAVCR2)." (PMID 34249015, 2021). "We found that the expression level of GRWD1 was positively correlated with the expression levels of immune checkpoint-related genes (CD274, CTLA4, HAVCR2, LAG3, PDCD1, PDCD1LG2, SIGLEC15, and TIGIT) in most types of cancer, especially in STAD." (PMID 34616846, 2021). "Particularly, SPARC and SPP1 expression were positively correlated to DC-related markers CD86, NRP1, and inhibitory checkpoint markers including LAIR1, HAVCR2, and PDCDLG2 in most cancer types." (PMID 33240930, 2020).
cancer (continued). "Notably, genes such as HAVCR2, PDCD1LG2, CD274, and TIGIT exhibited the strongest positive correlations with STX7 across more than 20 cancer types, suggesting a role for STX7 in immune checkpoint-mediated regulation." (PMID 40999361, 2025). "However, each gene in different cancers positively correlated (p < 0.05) with either its mRNA expression or CNVs, e.g., TIGIT in ACC, LAG3 in UVM, HAVCR2 in LUSC, LAYN in OV and PDCD1 in BLCA." (PMID 40076932, 2025). "Therefore, further Pearson analysis was conducted to investigate the correlation between GPR65 and common cancer immune checkpoint inhibitors, such as CD200R1, CD47, HAVCR2, TIGIT, CTLA4, LAG3, and PD1." (PMID 38218960, 2024). "Although we did not observe higher expression of markers associated with effector cells in the ‘surrounding stromal leukocyte’ regions cf. ‘immune-rich cancer cell islet’ regions, we did observe higher expression of IC markers such as LAG3, Tim-3 (HAVCR2), VISTA, and PD-L1 in the surrounding stroma." (PMID 37046826, 2023). "Furthermore, positive correlations of PRC1 and some immune checkpoint genes (CD274, CTLA4, HAVCR2, LAG3, PDCD1, PDCD1LG2, TIGIT, and CD86) were observed in several cancers, especially BLCA, BRCA, KIRC, LUAD, LIHC, PRAD and THCA." (PMID 37563591, 2023). "Furthermore, the negative correlation between Genomics of Drug Sensitivity in Cancer (GDSC) (CH542802 and XMD14-99) with HAVCR2 expression indicated that the higher the expression of LINC00467 was, the less sensitive the CH542802 and XMD14-99 drugs were." (PMID 37078359, 2023). "Moreover, we found that KIF18A had a positive correlation with immune checkpoints, such as PD-1, PD-L1, CTLA4, TIGIT, LAG3, HAVCR2, and PDCD1LG2 in a great many cancers." (PMID 36830695, 2023). "HAVCR2 expression correlated with OS, PFI, and DSS in pan-cancer." (PMID 36081997, 2022). "It was found that HAVCR2 gene expression was noticeably related to TMB in SKCM (p = 0.031), CESC (p = 0.013), PRAD (p = 0.038), and UVM (p = 0.028) in eight prognosis-related cancers." (PMID 36081997, 2022). "In 33 cancer types, TIGIT and HAVCR2 expression had positive correlations with GBP1 expression." (PMID 35222540, 2022). "Furthermore, TOP2A was positively associated with expression of immune checkpoints (CD274, CTLA4, HAVCR2, LAG3, PDCD1 and TIGIT) in most cancer types." (PMID 35778520, 2022). "The HAVCR2/TIM-3 pathway represents an intriguing target and could further shape the landscape of cancer immunotherapy." (PMID 36081997, 2022). "In addition, we studied the relationship between the expression of KCC2 (SLC12A5) and NKCC1 (SLC12A2) in pan-cancer and immune checkpoint genes, including SIGLEC15, IDO1, CD274, HAVCR2, PDCD1, CTLA4, LAG3, and PDCD1LG2." (PMID 35372048, 2022). "Furthermore, CCNA2 is positively associated with expressions of immune checkpoints (CD274, CTLA4, HAVCR2, LAG3, PDCD1, and TIGIT) in most cancer types." (PMID 35480884, 2022). "Besides, our research manifested the correlation of SLC7A11 with 8 IC genes, namely CD274 (also known as PD-L1), HAVCR2, LAG3, SIGLEC15, PDCD1LG2, CTLA4, PDCD1, and TIGIT in 33 cancer types." (PMID 36267158, 2022). "Malignant tumors may avoid immune destruction by activating immune checkpoint target genes (e.g., PD-1, PD-L1, CTLA-4, TGF-β, and HAVCR2)." (PMID 36275676, 2022). "CCNA2 was positively correlated with expressions of CD274, CTLA4, HAVCR2, LAG3, PDCD1, and TIGIT in most cancer types, which indicated the CCNA2 expression may act as a marker after immunotherapy." (PMID 35480884, 2022). "Cancer cells can express ligands for T cell inhibitory receptors such as PDCD1 (PD-1) (ligand is CD274 [PD- L1]), CTLA-4 (ligands are CD80 and CD86), and HAVCR2 (aka TIM3) (ligand reported to be GAL9) to inhibit T cell activation and cytolytic T cell responses." (PMID 28822103, 2018).
cancer (continued). "It was identified that HAVCR2 had positive infiltration scores in all cancer types, whereas a negative infiltration score was noted for CXCL13 (in LGG and DLBCL), LAG3 (in DLBCL and AML), LAYN (in CHOL, KICH, AML, LGG, PCPG, THCA and UCS), PDCD1 (in DLBCL, AML and THYM) and TIGIT (DLBCL and AML)." (PMID 40076932, 2025). "In the context of cancer and chronic infection, CD8+ T cells may undergo exhaustion or dysfunction, marked by the upregulation of immune checkpoints like PD-1(PDCD1), CTLA4, LAG3, TIGIT, and TIM3(HAVCR2), impairing their anti-tumoral function." (PMID 39247201, 2024). "Additionally, high co-expression of HAVCR2 and MSLN have been shown to be prevalent in several cancers and may also be vulnerable to the use of CAR-T therapies." (PMID 39174744, 2024). "In addition, the DiNiro networks also uncovered several molecular interactions in mouse CD8+ T cells: (i) identifying the regulatory factor of HAVCR2, the NR4A1 gene (also called Nur77), which is a known critical mediator of T cell dysfunction and exhaustion in chronic inflammation and cancer." (PMID 36879901, 2023). "We further explored the correlation between the expression of LIPT1 and eight immune checkpoints (PD-L1, CTLA4, HAVCR2, LAG3, PDCD1, PDCD1LG2, SIGLEC15, and TIGIT), and found that LIPT1 levels were correlated with the expressions of these immune checkpoints, especially PD-L1, in most cancer types." (PMID 35837286, 2022). "The negative correlation between Cancer Therapeutics Response Portal (CTRP) drug sensitivity and the expression of HAVCR2 and TIGIT also showed that the higher the expression of LINC00467 was, the less sensitive CTRP drugs were, such as I-BET151, SR-II-138A, and triazolothiadiazine." (PMID 37078359, 2023).
infection (173 papers, 2007 to 2026). The state of being infected such as from the introduction of a foreign agent such as serum, vaccine, antigenic substance or organism. "Results herein fit within this scenario by showing that the expression level of HAVCR2 following infection is at least partially determined by a polymorphism that also affects susceptibility to HIV-1." (PMID 25180498, 2014). "To assess whether the modulatory effect of rs4704846 on HIV-1 susceptibility is exerted through changes in HAVCR2 expression, we performed an in vitro infection assay." (PMID 25180498, 2014). "Meanwhile, the expressions of Slc11a1, Havcr2, Ccl12, Sirt1, Ifng, Ccl3, and Trem2 were higher during the whole infection process." (PMID 40170749, 2025). "In our study, the statistically significant upregulation of Havcr2 (Tim-3) at one and ten days p.i. is probably related with the evidence of NK cells relevance in the early infection." (PMID 34281214, 2021). "EMSA and DNA pull-down assay showed that BMDC infection with LDPm induced Ets1, Ets2, USF1, and USF2 binding to the mouse HAVCR2 promoter." (PMID 37202419, 2023). "Genes specifically involved in the repression of viral replication such as HAVCR2, TDRD7, UBA7, UBE2L6 and RNASEL were first found in the comparison of DEGs between the two infections VN751 and IC89." (PMID 34671358, 2021). "Conversely, CpG sites related to Slc11a1, Havcr2, Ccl11, Ccl12, Sirt1, Ifng, Ccl3, Ror2, and Trem2 maintained lower methylation levels throughout the infection compared to noninfected samples." (PMID 40170749, 2025). "For instance, HAVCR2 involved in NFAT dephosphorylation was not significantly regulated in MA08 infection and was accompanied by upregulation of IL2 and downregulation of NFATC2 (nuclear factor of activated T cells, cytoplasmic 2)." (PMID 34671358, 2021).
immune dysfunction (26 papers, 2013 to 2025). "HAVCR2 was reported to mediate T-cell depletion and immune dysfunction." (PMID 36106123, 2022).
adenocarcinoma (9 papers, 2018 to 2025). A common cancer characterized by the presence of malignant glandular cells. "Immune checkpoint blockade (ICB) gene analysis further revealed significant upregulation of LAG3, PDCD1, PDCD1LG2, HAVCR2, and CD274 in the solid pattern adenocarcinomas." (PMID 38505588, 2024).